MIR1250 (microRNA 1250)
Synonyms: hsa-mir-1250; MIRN1250; mir-1250
Gene: MicroRNA gene on chromosome 17 (81,133,196 to 81,133,308, reverse strand). Ensembl gene ENSG00000221025.
Homologues: Orthologues: chimpanzee ptr-mir-1250 (100% identical).